TRAF3IP2-AS1 (TRAF3IP2 antisense RNA 1)
Synonyms: C6UAS; BetaFAAR; C6orf3; NCRNA00248; TRAF3IP2-AS2
Gene: Long non-coding RNA gene on chromosome 6 (111,483,389 to 111,598,784, forward strand). Ensembl gene ENSG00000231889.
Diseases named in the same sentence as TRAF3IP2-AS1 in open-access papers:
TRAF3IP2-AS1 is named in the same sentence as 3 diseases in open-access papers, as found by Europe PMC text mining. Sharing a sentence is not in itself a finding about the gene and the disease. The quoted sentences say what the papers report.
translocation renal cell carcinoma (1 paper, 2022). "In our previous study, we found that lncRNA TRAF3IP2 antisense RNA 1 (TRAF3IP2-AS1) could play a critical role in the progression of NONO-TFE3 translocation renal cell carcinoma (NONO-TFE3 tRCC)." (PMID 35897085, 2022).
TRAF3IP2-AS1 also shares sentences with these, for which no sentence is quoted: glioma (1 paper); sarcopenia (1).